SIRT3 (sirtuin 3)
Diseases named in the same sentence as SIRT3 in open-access papers (continued):
Sharing a sentence is not in itself a finding about the gene and the disease.
nonalcoholic fatty liver disease (19 papers, 2016 to 2026). "Studies have shown that by inhibiting the expression of CD38 and increasing NAD+ concentration, SIRT3 concentration can be increased to clear ROS and reduce lipid accumulation, thereby inhibiting the development of non-alcoholic fatty liver disease." (PMID 38862726, 2024). "The Sirt3/FOXO3a pathway was reported to promote autophagy in liraglutide-treated mice with non-alcoholic fatty liver disease and in a rat model of exsanguinating cardiac arrest treated by emergency preservation and resuscitation." (PMID 35938164, 2022). "PCA treatment in nonalcoholic fatty liver disease (NAFLD) activated SIRT3 partly by suppressing fatty acid metabolism, mediated by ACSF3." (PMID 34790246, 2021). "In contrast, the Sirt3 co-expressed gene sets in the hippocampus were enriched for ribosomal proteins, translation regulation, proteasome regulation as well as non-alcoholic fatty liver disease and vesicle-mediated transport pathways." (PMID 30871457, 2019). "The latest studies demonstrated that DMY elevated SIRT3 expression to improve hypoxic hypoxia-induced memory and to attenuate the hepatic injury in nonalcoholic fatty liver disease." (PMID 30200365, 2018). "The latest study indicated that DMY ameliorated nonalcoholic fatty liver disease through a SIRT3-depedent mechanism." (PMID 30200365, 2018). "Furthermore, for non-alcoholic fatty liver disease, SIRT3 overexpression can protect liver cells by promoting BNIP3-mediated-mitophagy and reducing mitochondrial apoptosis, thus effectively treating non-alcoholic cirrhosis." (PMID 34912814, 2021). "Taken together, SIRT3 ameliorates lipotoxicity in hepatocytes, which might be a potential target for the treatment of nonalcoholic fatty liver disease." (PMID 31160717, 2020). "Similarly, DHY increased SIRT3 expression to ameliorate nonalcoholic fatty liver disease." (PMID 32933152, 2020). "Sirt3 can activate BNIP3-dependent mitophagy via the ERK-CREB signaling pathway, protecting hepatocytes in non-alcoholic fatty liver disease." (PMID 35938164, 2022). "Recent report emphasized that pharmacological activation of the SIRT3/ACSF3 pathway was an effective approach to alleviate NAFLD and protocatechuic acid was a novel candidate therapy for non-alcoholic fatty liver disease." (PMID 36205594, 2022). "SIRT3 activates ERK-CREB signaling to promote BNIP3 activity, thus inducing BNIP3 regulated mitotic resistance to nonalcoholic fatty liver disease." (PMID 32724473, 2020). "In nonruminants, there have been some trials to mitigate nonalcoholic fatty liver diseases by targeting SIRT3." (PMID 34208809, 2021).
diabetic nephropathy (18 papers, 2017 to 2026). "Across multiple models, activation of Sirt3 has been associated with inhibition of ferroptosis, corresponding to improved outcomes in diabetic nephropathy, reduced doxorubicin cardiotoxicity, and attenuation of femoral head osteonecrosis." (PMID 41301780, 2025). "SIRT3 deficiency has been reported to facilitate the mesenchymal transition of tubular epithelial cells, contributing to fibrosis in diabetic kidney disease." (PMID 39911234, 2024). "SIRT3 is a major mitochondrial deacetylase and SIRT3 deficiency leads to the abnormal glycolysis of diabetic nephropathy." (PMID 34983623, 2022). "Indeed, in mice models of diabetic nephropathy, SIRT3 knockdown led to a more fibrogenic phenotype associated with the induction of abnormal glycolysis." (PMID 39000044, 2024). "Regarding diabetic nephropathy, SIRT3 dysfunction was a crucial step in fibrosis development due to endothelial-to-mesenchymal transition (EndMT) in the kidneys of diabetic mice." (PMID 39000044, 2024). "N-acetylcysteine has been demonstrated to alleviate ferroptosis in diabetic nephropathy by maintaining mitochondrial redox homeostasis, It achieves this by activating the Sirtuin 3 (SIRT3)- SOD2/GPX4 pathway." (PMID 38155662, 2023). "Amniotic fluid stem cell (AFSC) transplantation is a promising therapeutic strategy for the treatment of diabetic nephropathy, and sirtuin-3 (SIRT3) is a new mitochondrial protective factor." (PMID 34380561, 2021). "SIRT-3 activity significantly decreased in an animal model of diabetic nephropathy resulting in enhanced mesangial cells hypertrophy." (PMID 32519752, 2020). "The recent studies mainly focused on the effect of SIRT3 in acute kidney injury and diabetic nephropathy." (PMID 28465484, 2017). "Notably, SIRT3 has also been found to mitigate fibrosis in diabetic kidney disease through the Fibroblast Growth Factor Receptor 1 pathway." (PMID 39911234, 2024). "Our results demonstrate the hitherto unknown renoprotective effect of SIRT3 against diabetic glomerular disease and suggest that the pharmacological modulation of SIRT3 activity is a possible novel approach to treating diabetic nephropathy." (PMID 32439965, 2020). "The regulation of SOD2 by SIRT3 has been widely described in kidney diseases models including renal ischemia/reperfusion (I/R), toxic-induced AKI as well as diabetic nephropathy." (PMID 39000044, 2024). "Contrarily to SIRT3, which was found to be downregulated in renal injuries, SIRT5 expression was found to be systematically increased in PTECs during AKI and in diabetic nephropathy." (PMID 39000044, 2024). "For example, DHM was reported to mediate the AMPK-PGC-1a-SIRT3 signaling pathway to improve skeletal muscle insulin sensitivity and promote autophagy by activating AMPK/mTOR signaling pathway, thereby reducing diabetic kidney injury and even delaying the progression of diabetic nephropathy." (PMID 38275711, 2024). "In addition, many new signaling molecules that regulate kidney fibrosis have been found, such as protective nature of endothelial glucocorticoid receptors, endothelial SIRT3, endothelial FGFR1 against renal fibrosis and, podocyte–glucocorticoid receptor signaling in protecting diabetic nephropathy." (PMID 35166173, 2022). "Similarly, DMY could also mediate the AMPK-PGC-1α-SIRT3 signaling pathway to improve skeletal muscle insulin sensitivity and promote autophagy by activating the AMPK/mTOR signaling pathway, which can alleviate diabetic kidney injury and even retard the progression of diabetic nephropathy." (PMID 37732125, 2023).
Huntington disease (18 papers, 2013 to 2025). Huntington disease (HD) is a rare neurodegenerative disorder of the central nervous system characterized by unwanted choreatic movements, behavioral and psychiatric disturbances and dementia. "To this, SIRT3 is implicated in the pathogenesis of AD, PD, amyotrophic lateral sclerosis, and Huntington’s disease." (PMID 35008438, 2021). "The study identified reduced expression of SIRT3 because of mutant protein huntingtin (Htt), which causes Huntington’s disease." (PMID 25907989, 2015). "Recently, SIRT3 was found to confer neuroprotection in Huntington's disease by regulation of mitochondrial dynamics." (PMID 34938344, 2021). "Apart from these, a recent study elucidated the involvement of SIRT3 in protection against neurodegeneration in Huntington’s disease." (PMID 25907989, 2015). "A recent report found that a resveratrol derivative, trans-(-)-ε-viniferin, is able to increase SIRT3 expression and provide protection in cell models of Huntington’s disease (HD)." (PMID 24046746, 2013).
kidney damage (18 papers, 2016 to 2025). "Eight-week-old mice were injected with ADR at a dose that induces mild nephropathy in WT mice to allow to better detect the differences caused by Sirt3 deficiency." (PMID 37816025, 2023). "Consistently, our data show that VEGFA and VEGFR2 are significantly reduced in the glomeruli of Sirt3-deficient mice, even prior to kidney damage induction." (PMID 37816025, 2023). "The present study demonstrates that Sirt3 deficiency is a predisposing factor for the aggravation of oxidative stress and mitochondrial abnormalities, leading to worsening kidney damage in response to chronic HFD feeding." (PMID 35955472, 2022). "In a separate experiment involving kidney I/R, researchers discovered that SIRT3, a crucial deacetylase enzyme located within mitochondria, plays a pivotal role in mitigating kidney damage." (PMID 37635869, 2023). "t-BHQ treatment also alleviates contrast-induced nephropathy by activating the Nrf2/Sirt3 signaling pathway." (PMID 34211633, 2021). "In order to study whether Sirt3 deficiency holds a detrimental role in the development of CKD, we induced nephropathy by Adriamycin (ADR) injection in Sirt3-/- mice." (PMID 37816025, 2023). "Deficiency of SIRT3 reportedly aggravates lipid deposition and FAO dysfunction in cisplatin-mediated AKI, whereas the activation of SIRT3 improves the level of FAO by deacetylation of liver kinase B1 (LKB1) and activation of AMPK, which meets energy requirement and reduces the kidney damage." (PMID 39450927, 2024). "HIF-1α, the prototypical factor involved in the transcriptional responses to cellular hypoxia, was upregulated in both the glomerular and tubular compartments at nuclear levels in Sirt3-deficient mice prior to eliciting kidney damage, and was not further increased upon the induction of renal injury." (PMID 37816025, 2023). "Our findings suggested that Nrf2 plays an important role in the regulation of the Sirt3/SOD2 antioxidative pathway, and t-BHQ may be a potential agent to ameliorate radiocontrast-induced nephropathy via activating the Nrf2/Sirt3/SOD2 signaling pathway in vitro and in vivo." (PMID 31929854, 2019). "Finding that nitrotyrosine staining was even higher in Sirt3-/- mice receiving ADR compared to KO mice receiving saline indicates that mice lacking Sirt3 experience excessive ROS production in the kidney of mice with induced nephropathy." (PMID 37816025, 2023). "Collectively, these data suggest that the hypoxic signaling triggered by the lack of Sirt3 is so pronounced that it cannot be further aggravated by the superimposition of ADR-induced kidney damage." (PMID 37816025, 2023). "Consistently, the increased accumulation of monocytes/macrophages was found in the kidneys of Sirt3−/− mice given the HFD, mostly in the renal interstitium, which could have contributed to kidney damage." (PMID 35955472, 2022). "Additionally, using SIRT1 and SIRT-3 knock out male mice may be needed to detect whether the observed exacerbated kidney damage in CS-exposed MI male mice is due to decreased SIRT-1 and SIRT-3 levels, consequently potential enhanced mitochondria dysfunction." (PMID 32519752, 2020). "The role of NOX4, but not TRX2 and SIRT3/SOD2 signaling pathway, in UUO and IRI-induced nephropathy has been reported." (PMID 35355864, 2022).
osteoarthritis (18 papers, 2020 to 2025). A noninflammatory degenerative joint disease occurring chiefly in older persons, characterized by degeneration of the articular cartilage, hypertrophy of bone at the margins and changes in the synovial membrane. "Next, the SIRT3 inhibitor also promoted ferroptosis and mitochondrial damage in the in vitro osteoarthritis model with the presence of PRDX3." (PMID 40757971, 2025). "Immunofluorescence results indicated that PRDX3 up-regulation induced the expression of both PRDX3 and SIRT3 in the in vitro model of osteoarthritis." (PMID 40757971, 2025). "Further elucidation of the role of PRDX3 and its relationship with the regulation of the SIRT3 pathway can facilitate the understanding of ROS accumulation and mitochondria-dependent ferroptosis and improve the clinical management of osteoarthritis." (PMID 40757971, 2025). "The SIRT3‐medicated post‐translational acetylation of the mitochondrial respiratory chain has therapeutic potential for the treatment of osteoarthritis (OA)." (PMID 36683245, 2023). "SIRT3 can also ameliorate osteoarthritis by regulating chondrocyte autophagy by inhibiting the IL-1β-induced PI3K/Akt/mTOR signaling pathway." (PMID 37196115, 2023). "In another study, SIRT3 expression was decreased in a model of osteoarthritis and correlated with ROS production, and metformin treatment exerted a chondroprotective effect by promoting SIRT3 expression." (PMID 36081941, 2022). "It was reported that metformin protects against osteoarthritis through PINK1/Parkin-dependent mitophagy by up-regulating SIRT3 expression." (PMID 36387221, 2022). "In the present study, diverse experiments collectively verified that SIRT3 ameliorated osteoarthritis progression via reducing chondrocyte apoptosis as well as improving mitochondrial dysfunction." (PMID 34646424, 2021). "Studies have shown that DHM promoted SIRT3 in chondrocytes via the AMPK-peroxisome proliferator-activated receptor γ coactiva-tor-1 (PGC-1α)-SIRT3 signaling pathway in osteoarthritis rat." (PMID 35115939, 2021). "In this study, we demonstrated that the circFAM160A2 promotes mitochondrial stabilization and apoptosis reduction in osteoarthritis chondrocytes by targeting miR-505-3p and SIRT3 using a series of experiments in vitro and in vivo." (PMID 34646424, 2021). "This study is the first to examine the crucial role of the circFAM160A2-miR-505-3p-SIRT3 axis in osteoarthritis progression." (PMID 34646424, 2021). "Previous literature has shown that Sirt3 has an important protective effect on the pathophysiology of osteoarthritis by inhibiting the PI3K/Akt/mTOR signaling pathway." (PMID 34095262, 2021). "Subsequently, the mechanism of PRDX3 on SIRT3 in osteoarthritis was explored." (PMID 40757971, 2025). "However, the SIRT3 agonist reduced ferroptosis and mitochondrial damage in the in vitro osteoarthritis model with the intervention of si-PRDX3." (PMID 40757971, 2025). "Sh-PRDX3 down-regulated SIRT3 expression in the articular tissue of osteoarthritis mice." (PMID 40757971, 2025). "Moreover, sh-PRDX3 suppressed the protein expressions of both PRDX3 and SIRT3 in the articular tissue of osteoarthritis mice." (PMID 40757971, 2025). "Recently, we found that SIRT3 could ameliorate osteoarthritis via regulating chondrocyte autophagy and apoptosis through the PI3K/Akt/mTOR pathway." (PMID 34646424, 2021). "In addition, activation of SIRT3 can suppress osteoarthritis by maintaining mitochondrial metabolism stability." (PMID 32724473, 2020). "In a rat osteoarthritis model, the activation of Bax and caspase 3/9 and the downregulation of Bcl-2, which were induced by IL-1β in SIRT3-overexpressing chondrocytes, were significantly reduced, indicating that SIRT3 protected chondrocytes from IL-1β-induced apoptosis." (PMID 37196115, 2023). "PRDX3 up-regulation reduced SIRT3 ubiquitination, and si- PRDX3 induced SIRT3 ubiquitination in the in vitro model of osteoarthritis." (PMID 40757971, 2025).
osteoarthritis (continued). "Meanwhile, it was discovered that in the osteoarthritis model, PRDX3 induced SIRT3 expression level by inhibiting the ubiquitination of SIRT3." (PMID 40757971, 2025). "In the in vitro osteoarthritis model, PRDX3 up-regulation led to an increase in the protein expressions of PRDX3 and SIRT3, while si-PRDX3 suppressed PRDX3 and SIRT3 protein expressions." (PMID 40757971, 2025). "In the osteoarthritis model, PRDX3 induced SIRT3 expression to regulate ROS accumulation and mitochondria-dependent ferroptosis." (PMID 40757971, 2025). "Meanwhile, the SIRT3 inhibitor (10 μM of SRT AGK2) suppressed SIRT3 and GPX4 protein expressions and inhibited the effects of PRDX3 on ROS accumulation in the in vitro osteoarthritis model." (PMID 40757971, 2025). "In this study, the SIRT3 agonist (0.05 μM of SRT 1720 dihydrochloride) was used to induce SIRT3 and GPX4 protein expressions and attenuate the effects of si-PRDX3 on ROS accumulation in the in vitro osteoarthritis model." (PMID 40757971, 2025).
pancreatic cancer (16 papers, 2011 to 2025). "SIRT3 has also been reported to regulate iron metabolism in pancreatic cancer, where dysregulated iron homeostasis is a hallmark of malignancy." (PMID 39682281, 2024). "Accumulating evidence offers profound insights into the mechanistic role of SIRT3 (SIRT3) in regulating the diverse signaling pathways implicated in pancreatic cancer." (PMID 39682281, 2024). "Loss of SIRT3 in pancreatic cancer cells increases IRP1 binding to IREs, and the expression of its target gene TFR1, thereby disrupting cellular iron homeostasis." (PMID 37237500, 2023). "Similarly, another study claims that SIRT3 is associated with the regulation of pancreatic cancer progression through its modulation of the HIF-1α pathway." (PMID 39682281, 2024). "A deficiency of SIRT3 in renal tissue and pancreatic cancer cells leads to iron accumulation." (PMID 37237500, 2023). "Together, both in vitro and in vivo results demonstrated that SIRT3 functioned as a tumor suppressor in KRASG12D-driven pancreatic cancer." (PMID 41391757, 2025). "Correlative studies showed that pancreatic cancer patients with low SIRT3 expression exhibited higher degree of malignancy with poor clinical prognosis." (PMID 41391757, 2025). "Conversely, forced overexpression of SIRT3 inhibited pancreatic cancer cell proliferation both in vitro and in vivo." (PMID 41391757, 2025). "In our study, we found that a knockdown of SIRT3 by shRNA in pancreatic cancer cells led to a significant resistant to MRTX1133, whereas overexpression of SIRT3 enhanced the sensitivity of pancreatic cancer cells to MRTX1133." (PMID 41391757, 2025). "Knockdown of RCC1 in pancreatic cancer cells restored SIRT3 expression and impaired tumor formation in vivo." (PMID 41391757, 2025). "The exact role of SIRT3 in pancreatic cancer tumorigenesis in vivo and the relation between KRAS and SIRT3 remain to be investigated." (PMID 41391757, 2025). "Overexpression of SIRT3 inhibited pancreatic cancer proliferation in vitro and tumorigenesis in vivo." (PMID 41391757, 2025). "These new findings indicate that the down regulation of the RCC1/SIRT3 axis plays a significant role in KRAS-driven pancreatic cancer development." (PMID 41391757, 2025). "The repression of SIRT3 contributes to the metabolic reprogramming of pancreatic cancer cells, enhancing glycolytic flux and supporting tumor progression." (PMID 39682281, 2024). "In pancreatic cancer, the transcriptional silencing of SIRT3 by zinc finger E-box binding homeobox-1 (ZEB1) in cooperation with the methyl-CpG-binding domain protein 1 (MBD1) promotes a metabolic shift towards glycolysis." (PMID 39682281, 2024). "One such study reported that SIRT3 is pivotal in the carcinogenesis of pancreatic cancer by modulating the mitochondrial enzymatic functions critical for cellular metabolism and tumor progression." (PMID 39682281, 2024). "A recent report suggested that SIRT3 is also involved in the regulation of the electron transport chain (ETC) in pancreatic cancer, particularly through its modulation of mitochondrial complex II (CII) activity." (PMID 39682281, 2024). "Tris DBA’s capacity to modulate autophagy and reduce mitochondrial ROS highlights the potential ability of targeting SIRT3 to reverse the metabolic dysregulation commonly observed in pancreatic cancer." (PMID 39682281, 2024). "In conclusion, targeting SIRT3 emerges as a promising therapeutic approach in pancreatic cancer, given its multifaceted role in regulating mitochondrial metabolism, oxidative stress and key oncogenic pathways." (PMID 39682281, 2024). "The tumor-suppressive functions of SIRT3 in pancreatic cancer are also gaining attention, particularly regarding its regulation of cellular metabolism." (PMID 39682281, 2024).